DNMT3A (DNA methyltransferase 3 alpha)
Diseases named in the same sentence as DNMT3A in open-access papers (continued):
Sharing a sentence is not in itself a finding about the gene and the disease.
heart failure (28 papers, 2015 to 2026). Inability of the heart to pump blood at an adequate rate to meet tissue metabolic requirements. "CHIP was associated with prevalent heart failure (HF, OR 1.25 [95% CI 1.01-1.55], p = 0.04; especially for non-DNMT3A CHIP (OR 1.38 [95% CI 1.04-1.82], p = 0.02)." (PMID 41666166, 2026). "Concerning the loss of Dnmt3a, it was originally reported that Dnmt3a-knockout (KO) BMCs worsened heart function through an increased accumulation of macrophages and other immune cells in the myocardium in experimental heart failure." (PMID 40773119, 2025). "The presence of DNMT3A‐CHIP is associated with a significantly increased risk of heart failure, ischemic stroke, and mortality, with a 1.45‐fold higher prevalence in atrial fibrillation (AF) patients." (PMID 39006763, 2024). "The mechanism by which clonal hematopoiesis of TET2 and DNMT3A exacerbates atherosclerosis and heart failure is proposed to be that mutated macrophages become pro-inflammatory, leading to the growth of arterial plaques and myocardial damage." (PMID 38985383, 2024). "DNMT3A mutated monocytes from patients with heart failure have been shown to express higher mRNA levels of IL-1β, IL-6 and IL-8, macrophage inflammatory chemokines CCL3 and CCL4 and the inflammasome NLRP3." (PMID 36835370, 2023). "Another study also reported that CHIP with DNMT3A or TET2 mutations was associated with about two times higher risk of death combined with heart failure hospitalization in chronic heart failure of ischemic origin." (PMID 36807865, 2023). "Here we provide novel insights into the cell-intrinsic effect of DNMT3A mutations on circulating blood cells in the context of heart failure." (PMID 39196061, 2023). "Indeed, the circulating monocytes derived from patients with heart failure harboring DNMT3A mutations showed significantly higher expression of IL-1b, IL6, and CXCL2." (PMID 40773119, 2025). "Single‐cell transcriptome analysis in leukocytes from patients with heart failure indicates that DNMT3A mutations drive an increase in monocyte inflammatory gene expression, which can lead to enhanced proinflammatory activation and endothelial adhesion upon DNMT3A silencing in monocytes." (PMID 39006763, 2024). "Thus, DNMT3A CHIP mutations likely amplify heart failure by pleiotropic effects on inflammation and fibrosis." (PMID 38242884, 2024). "Importantly, previous studies have shown that individuals harboring either DNMT3A or TET2 CHIP-driver mutations in circulating blood cells experience increased mortality in the presence of heart failure or aortic valve stenosis." (PMID 38242884, 2024). "The activation of cardiac fibroblasts may lead to the initiation and further progression of diffuse cardiac fibrosis in patients with heart failure carrying DNMT3A CHIP-driver mutations." (PMID 38242884, 2024). "In this study, we demonstrate that monocytes derived from patients with heart failure carrying DNMT3A CHIP-driver mutations may contribute to the progression of cardiac fibrosis." (PMID 38242884, 2024). "In addition, mutations in TET2 or DNMT3A have demonstrated a profoundly increased mortality driven by the progression of heart failure." (PMID 38985383, 2024). "Circulating inflammatory cytokines were not measured in this group but, in a separate very small cohort of six patients with heart failure, the presence of DNMT3A mutation was associated with higher transcription of IL-1β and IL-6 when compared with patients with HF and no DNMT3A mutation." (PMID 33861346, 2021). "The presence of somatic mutations within TET2 or DNMT3A remained independently associated with adverse outcome (death or death combined with heart failure hospitalization) in addition to age, whereas hypertension was not independently associated in this multivariable model." (PMID 30566180, 2019).
heart failure (continued). "Furthermore, DNMT3A or TET2 mutations were associated with accelerated progression of heart failure (further reduction of left ventricular ejection fraction (LVEF), heart failure-related death or hospitalization) within a 3.5 years’ follow-up irrespective of ischemic/non-ischemic etiology." (PMID 35885518, 2022). "We primarily focused on the two most common CHIP‐driver mutations, DNMT3A and TET2, for which a prognostic role in heart failure is firmly established." (PMID 40702883, 2025). "Supporting the role of DNA methylation in heart failure, there are data that demonstrate that overexpression of DNMT3A reduces the expression of oxidative metabolic genes in H9c2 rat cardiomyoblasts." (PMID 37893188, 2023). "Specifically, it has been found that hematopoietic mutations in common driver genes, DNMT3A, TET2, and JAK2V671F, can accelerate experimental atherosclerosis and/or heart failure by generating a pool of myeloid cells with an augmented proinflammatory profile." (PMID 36414855, 2023). "In addition to providing, to our knowledge, the first evidence for the cell-intrinsic effects of DNMT3A mutations on peripheral blood cell subsets in patients with heart failure, the experimental approach may be helpful to address the effects of the various CHIP driver genes in a disease context." (PMID 39196061, 2023). "The underlying mechanisms by which CHIP and its mutations in ASXL1, DNMT3A, TET2, or JAK2 are related to heart failure development and progression are not well understood." (PMID 35657494, 2022). "In the sensitivity analyses, patients with non-DNMT3A driver genes—but not those with top CHIP driver genes or large clones—had a significantly increased risk of heart failure." (PMID 39836422, 2025). "We found that the expression of both HBEGF and AREG was significantly higher in circulating monocytes of heart failure patients carrying DNMT3A CHIP-driver mutations compared to No-CHIP carriers." (PMID 38242884, 2024). "Consequently, we confirmed an increased diffuse cardiac fibrosis in mice carrying hematopoietic DNMT3A CHIP-driver mutations subjected to myocardial infarction, as well as in patients with established heart failure." (PMID 38242884, 2024). "To further investigate the impact of harboring DNMT3A CHIP-driver mutations on diffuse cardiac fibrosis in humans, we determined cardiac fibrosis using cardiac magnetic resonance imaging with myocardial mapping in patients with heart failure." (PMID 38242884, 2024). "In this study, we combined single-cell RNA sequencing (scRNA-seq) with Oxford Nanopore long-read sequencing to identify DNMT3A mutant cells within the circulating immune cells from patients with heart failure and determined the gene expression at single-cell level." (PMID 39196061, 2023). "Transcriptome profiling analysis of peripheral blood mononuclear cells 6 patients with heart failure (HF) harboring DNMT3A CH-driver mutations and 4 patients with HF and no DNMT3A mutations by single-cell RNA-sequencing." (PMID 34279740, 2021). "Hematopoietic mutations in epigenetic regulators like DNA methyltransferase 3 alpha (DNMT3A), play a pivotal role in driving clonal hematopoiesis of indeterminate potential (CHIP), and are associated with unfavorable outcomes in patients suffering from heart failure (HF)." (PMID 38242884, 2024). "Moreover, in heart failure patients upregulation of DNMT3a and DNMT3b expression was observed." (PMID 38314203, 2024). "In patients with heart failure, peripheral blood monocytes of patients carrying DNMT3A mutations have demonstrated a significant upregulation of inflammatory genes compared with those of patients without DNMT3A mutations." (PMID 37457265, 2023).
heart failure (continued). "Interestingly, mutations of ASXL1, TET2, and JAK2, but not DNMT3A were found to be a risk factor for heart failure in this study." (PMID 35885518, 2022). "This study uncovers a critical link between DNMT3A-driven CHIP and heart failure and, in particular, it shows that DNMT3A inactivation in monocytes boosts the release of HB-EGF, which activates fibroblasts inducing diffuse fibrosis in the heart." (PMID 38242884, 2024). "Furthermore, the DNA methyltransferase (DNMT) family of proteins, particularly DNMT3A and DNMT3B, plays a pivotal role in heart failure and myocardial fibrosis by regulating gene expression through DNA methylation." (PMID 40290189, 2025). "Thus, an impairment or reduction in DNMT3A-mediated DNA methylation, which produces a reduction in HIF-1α, should limit the heart’s ability to sustain injury leading to heart failure." (PMID 37893188, 2023). "There are data suggesting that DNMT3a and DNMT3b are not operative in heart failure, as DNMT3a/3b ablation in mice did not increase in heart failure after increased cardiac loading from aortic constriction." (PMID 37893188, 2023). "In order to gain potential insights into the detrimental effect of the combination of both, the presence of harbouring CHIP mutations and LOY ≥17%, on prognosis in patients with heart failure, a paired analysis of LOY and Y cells in patients with and without DNMT3A mutations was performed." (PMID 40702883, 2025). "Together, these data decipher the specific pro-inflammatory gene activation in DNMT3A mutant monocytes, demonstrating additional molecules, such as proteoglycan serglycin, phagolysosome genes, MCEMP1 and calreticulin, previously undescribed for CHIP-carrying patients with heart failure." (PMID 39196061, 2023). "The hypermethylation of CpG islands which was observed in human heart failure might not be due to catalytic activity of Dnmt3a or Dnmt3b in cardiomyocytes." (PMID 26098432, 2015). "Notably, DNMT3a and DNMT3b do not play a role in heart failure." (PMID 40290189, 2025).
Tatton-Brown-Rahman syndrome (27 papers, 2019 to 2025). "High-throughput sequencing revealed a specific mutation in the DNMT3A gene (NM_175629.2:c.2408 + 1G > A) associated with Tatton-Brown–Rahman syndrome." (PMID 39902084, 2024). "Pathogenic variants in DNMT3A cause Tatton-Brown-Rahman syndrome by focal, canonical hypomethylation of genomic DNA." (PMID 38894719, 2024). "Tatton-Brown-Rahman syndrome (TBRS) is a rare congenital genetic disorder caused by autosomal dominant pathogenic variants in the DNA methyltransferase DNMT3A gene." (PMID 38845031, 2024). "For example, constitutional loss-of-function (LoF) variants of DNMT3A lead to decreased global DNAm and altered hematopoiesis in a condition referred to as Tatton-Brown-Rahman syndrome (TBRS; OMIM #615879)." (PMID 36814905, 2023). "Since mutations of the DNMT3A ADD domain are found in patients with Tatton-Brown-Rahman syndrome and hematologic malignancy, the ADD-H3K4me0 interaction is important not only in oocytes but also in somatic cells." (PMID 37527244, 2023). "Pathogenic variants of DNMT3A have been implicated in Tatton-Brown-Rahman syndrome, an overgrowth disorder with macrocephaly and intellectual disability." (PMID 37303757, 2023). "Here, we focused on rare early onset developmental disorders with loss-of-function (LoF) pathogenic variations in DNMT3A (Tatton-Brown-Rahman syndrome; TBRS) and in DNMT3B (Immunodeficiency Centromeric instability and Facial dysmorphism; ICF)." (PMID 33916664, 2021). "Tatton-Brown–Rahman syndrome (TBRS) is caused by a mutation in DNMT3A, a gene that is also associated with Sotos syndrome, which is caused by haploinsufficiency of NSD1, an HMT that catalyzes the demethylation of histone H3 at K36 (H3K36m22)." (PMID 32493501, 2020). "Given that haploinsufficiency of DNMT3A has been ruled in as a mutational mechanism for Tatton-Brown–Rahman syndrome, it seems likely that all pathogenic variants will prove to be loss of function." (PMID 31575610, 2019). "Tatton-Brown–Rahman syndrome (MIM #615879) is an autosomal dominant genetic condition resulting from germline heterozygous mutations in the DNMT3A gene." (PMID 31575610, 2019). "A series of germline mutations in DNMT3A were discovered in patients with growth syndromes, Tatton-Brown-Rahman syndrome (TBRS) and microcephalic dwarfism (MD)." (PMID 31091831, 2019). "A recent preprint has shown that loss-of-function mutations in DNMT3A, which cause Tatton-Brown-Rahman overgrowth syndrome, also lead to a higher ticking rate of the epigenetic aging clock." (PMID 31409373, 2019). "Tatton-Brown-Rahman syndrome is a rare autosomal dominant hereditary disease caused by pathogenic variants in the DNMT3A gene, which is an important participant in epigenetic regulation, especially during embryonic development, and is highly expressed in all tissues." (PMID 38804405, 2024). "Although the cause of this discrepancy is currently unknown, it is noteworthy that mutations in the PWWP domain of human DNMT3A can lead to both overgrowth (Tatton-Brown-Rahman syndrome) and microcephalic dwarfism." (PMID 37527244, 2023). "Germline heterozygous mutations in the genes encoding core PRC2 members (EZH2, EED and SUZ12), NSD1 and DNMT3A have been implicated in a triad of highly phenotypically related human developmental disorders: Weaver syndrome, Sotos syndrome and Tatton-Brown–Rahman syndrome, respectively." (PMID 31575610, 2019). "Tatton-Brown-Rahman syndrome (TBRS) is a rare overgrowth/intellectual disability disorder caused by DNMT3A variants." (PMID 41384217, 2025). "Within this spectrum, Tatton-Brown-Rahman syndrome (TBRS) was delineated in 2014 in individuals with overgrowth harboring heterozygous variants in DNMT3A." (PMID 41384217, 2025).
Tatton-Brown-Rahman syndrome (continued). "The increased methylation of DNMT3A target genes observed in the proband’s sample points towards a gain-of-function effect of the variant, contrasting with the inactivation caused by loss-of-function alterations commonly seen in other neoplasia and in patients with Tatton-Brown-Rahman syndrome." (PMID 33182397, 2020). "On the one hand, germline de novo loss-of-function variants in DNMT3A cause Tatton-Brown-Rahman syndrome (TBRS), an autosomal dominant condition characterized by overgrowth, intellectual disability and distinctive facial appearance." (PMID 33182397, 2020). "In the human brain, downregulation of nuclear DNMT1 is linked to Parkinson’s disease (PD) and dementia with Lewy bodies (DLB), whereas a mutation in the DNMT3a gene is linked to autism spectrum disorder (ASD) and Tatton-Brown–Rahman syndrome (TBRS)." (PMID 40940739, 2025). "Inborn DNMT3A hemizygosity (Tatton-Brown-Rahman syndrome) results in leukocyte features with increased neutrophil-to-lymphocyte ratio, reduced B-cell progenitors, and elevated IL-642." (PMID 38238335, 2024). "Epigenetic age acceleration has previously been reported in Sotos syndrome and Tatton-Brown-Rahman syndrome (TBRS), which are caused by loss of function variants in two genes encoding epigenetic regulators, NSD1 and DNMT3A, respectively." (PMID 35361921, 2022). "Tatton Brown-Rahman syndrome (TBRS), another childhood overgrowth disorder that is defined by germline mutations in DNA (cytosine-5)-methyltransferase 3A (DNMT3A), shares similar clinical features with Sotos syndrome." (PMID 33937229, 2021). "DNMT3A related overgrowth syndrome, also known as Tatton-Brown-Rahman syndrome (TBRS) is an autosomal dominant condition characterized by overgrowth, distinctive facial appearance, and intellectual disability." (PMID 31091831, 2019). "This was consistent with these diseases being distinct, although extensive overlap of clinical signs between SETD2-associated phenotypes and other overgrowth syndromes related to NSD1, EZH2 or DNMT3A in Sotos, Weaver and Tatton-Brown-Rahman syndromes, respectively, has been reported." (PMID 33916664, 2021). "Interestingly, the methylation episignatures of LLS individuals and of other non-imprinting epigenetic disorders associated with congenital overgrowth such as Sotos syndrome and DNMT3A-overgrowth syndrome (Tatton-Brown-Rahman syndrome; MIM:615879) demonstrate predominant hypomethylation." (PMID 37166351, 2023).